CD74 (CD74 molecule)
Diseases named in the same sentence as CD74 in open-access papers (continued):
Sharing a sentence is not in itself a finding about the gene and the disease.
tumor (continued). "Although CD74 expression was not significantly higher in hybrid cells than tumor cells at the protein level, it was highly enriched in cells within circulation compared to those within the primary tumor." (PMID 39030653, 2024). "Intriguingly, we observed that the tumor niche contains CD74 negative tumor cells and a lower proportion of CD74 positive cells." (PMID 39001552, 2024). "We further verify that expression of three genes identified from our scRNA-seq analyses, thymosin beta 10 (TMSB10), CD74 and GPX1, are expressed at the protein level in hybrid cells within patient-matched primary tumor and peripheral blood (n = 4; n = 1 GEP class 1 and n = 3 GEP class 2)." (PMID 39030653, 2024). "We now know that MIF is expressed by immune, stromal, and tumor cells, and binds to three known non-cognate receptors in addition to CD74, with implications in normal and aberrant immune responses." (PMID 38730725, 2024). "In interactions with epithelial cells, the binding of MIF to CD74 and CD44 may affect cell proliferation, migration, and functions in pathological states, such as promoting tumor cell growth and metastasis in the tumor microenvironment." (PMID 38720887, 2024). "Taken together, TAM‐derived MIF may promote CD74 activation, thus facilitating the PI3K‐STAT3‐PD‐L1 signalling pathway, ultimately resulting in immune escape and tumour progression." (PMID 39113235, 2024). "Tumor cells (n=38284; 31.2%, n=8; range 22.5-37.2% per PDAC) were annotated into 7 different subtypes, based on the expression of Pan-Ck, cytokeratin 7 (Ck-7), CD44, S100A4, PTX3, CA-IX, CD74." (PMID 39575252, 2024). "This suggests that FABP6+ tumor cells may utilize CD74 to interact with CD44 on Treg cells, potentially promoting the immunosuppressive function of Treg cells and facilitating tumor development." (PMID 38277205, 2024). "Furthermore, the iso-ligand receptors MIF-(CD74+CXCR4) and MIF-(CD74+CD44) regulate T/NK cells, potentially facilitating tumor cell evasion of immune surveillance." (PMID 39712016, 2024). "The tumor and immune cells in TNBC express high levels of CD74; however, the function of this receptor in the tumor environment has not been extensively characterized." (PMID 39576827, 2024). "The interaction between CD74 and CD44 may influence tumor cell behavior through the regulation of cell-matrix interactions, cell adhesion, migration, and infiltration pathways." (PMID 38277205, 2024). "In addition, GJB2 was found overexpressed in CD74- and CLTC-ROS1+ tumor specimens and cell lines, which positively correlates with patients presenting a poor prognosis." (PMID 39737401, 2024). "In the subsequent analysis of the potential pathways between GrB+ B cells and tumor cells, the most important incoming and outgoing L-R pairs were the signaling complexes, macrophage migration inhibitory factor (MIF) -(CD74 + CXCR4) and lymphotoxin-alpha (LTA)–(LTB + LTBR), respectively." (PMID 38386050, 2024). "Moreover, MIF-(CD74 + CD44) signaling between fibroblasts and cholangiocytes, dendritic cells and T cells was significantly enhanced in tumor tissue." (PMID 38702814, 2024). "Neutrophils of cluster 3 (Neu_C3_VEGFA, CD74+/HLA‐DRA+) displayed a mixed phenotype with angiogenesis, lipid metabolism‐related, and antigen‐presentation characteristics and they enriched in both the leading‐edge and tumor‐core region." (PMID 39716897, 2024). "The L–Rs including the MIF-(CD74+CXCR4) and collagen/fibronectin/laminin-CD44 interactions in MTs may create a tumor immunosuppressive microenvironment." (PMID 38414027, 2024). "Therefore, we proposed that the occurrence of the elevated CD74 isoform ratio that signifies the enrichment of CD8+CXCL13+ Tex cells and C1QC+ TAMs generally exists in the tumor and lymph node of ESCC patients." (PMID 39312471, 2024).
tumor (continued). "The top 100 genes found to be co-expressed with CD74 were examined using GEPIA2.0, finding that the top five genes (HLA-DMA, HLA-DPA1, HLA-DPB1, HLA-DRA, and HLA-DRB1) were highly correlated with CD74 in most tumor types." (PMID 38582956, 2024). "The lack of CD74 in mature B cells did not affect the tumor load nor the phenotype of the infiltrating DCs." (PMID 39576827, 2024). "Using FACS analysis, we observed that mice inoculated with CD74‐Over KLN205 cells exhibited a decrease in the relative proportions of CD4+ T cells, CD8+ T cells and GZMK+ Perforin+CD8+ T cells in the blood, spleen, tumour tissue and lymph nodes." (PMID 39113235, 2024). "The PLOD2 + SAA1 + tumor cells could communicate with other cells through ligand-receptor pairs like SPP1-CD44, MIF-(CD74 + CXCR4), and MDK-LRP1." (PMID 38951896, 2024). "The transition from C1 or C3 to C2 may explain the significant immune activation that occurred in CD74-lo group and further support that AK104 therapy efficiently altered the tumor immune microenvironment and increased immune cell infiltration." (PMID 38280003, 2024). "Conversely, many genes have broad, often bi-/multimodal distribution (for example CD44, CCND1 and CD74 in tumour and STAT1 in both compartments for all p16/HPV subgroups), potentially reflecting spatial context – tumour core versus tumour periphery or tumour-adjacent versus more distant stroma." (PMID 39328208, 2024). "Furthermore, the protein level of CD74 expression was found to be expressed along with ALDH compared to the moderate expression level of CD24 and CD44 in the PDX tumor models." (PMID 39056676, 2024). "Taken together, these results suggest that CD74 expressed in DCs, but not in B cells, is crucial for the regulation of immune cell suppression at the tumor site." (PMID 39576827, 2024). "Concomitant with the overexpression of AQP4, genes related to the immune system were also over-expressed, such as CD74, HES1, CALD1, and HEBP2, indicating AQP4 may relate to immune factors of tumor progression." (PMID 36599974, 2023). "In conclusion, we provide the preclinical evidences showing anti-CD74 CAR-T cell therapy is an effective treatment approach for MCL patients warranting further development and exploration of combination therapies to augment tumor-specific CD74 expression." (PMID 37740214, 2023). "In tumor-infiltrating macrophages we also observed increased activation of cytokine-responsive genes IFITM3, CCR1 and UBB (FDR=10-4), as well as upregulation of genes involved in MHC Class II presentation H2-Aa, H2-Ab1, H2-Eb1 and CD74 (FDR=0.0015)." (PMID 36911698, 2023). "CD74‐MIF signaling plays an important role in immunosuppression, indicating that Macro_APOE/CTSZ may recruit Treg to infiltrate tumor tissue to inhibit antitumor immune responses." (PMID 36587392, 2023). "As a result, we found that CD163, CD74, S100A4, S100A12, HLA-DRA, and HLA-DRB1, which are usually highly expressed in myeloid cell, were also highly expressed in tumor cells of cluster 6; thus, we termed this cluster myeloid-like tumor cells." (PMID 37138326, 2023). "Intercellular interaction analysis suggested that MFAP5 + fibroblasts could reciprocally communicate with C1QC + macrophages and other myeloid cells to remodel unfavorable conditions via MIF/CD74, IL34/CSF1R, and other tumor-promoting signaling pathways." (PMID 37344903, 2023). "Next, the results of cell-cell communication analysis suggested that pericytes interact with broad immune cells via MDK-NCL pathways in metastasis samples, MIF-(CD74+CXCR4) and MIF-(CD74+CC44) interaction especially occurred between different cell types in tumor and normal samples." (PMID 37335089, 2023). "The present study investigated CD74 expression in B-NHL cell lines and patient tumor samples." (PMID 36634212, 2023).
tumor (continued). "Furthermore, we verified that hybrid cells within the primary tumor and in peripheral blood express TMSB10, CD74 and GPX1 at the protein level, and that TMSB10 and GPX1 are significantly upregulated in disseminated hybrid cells compared to CTCs." (PMID 38106024, 2023). "The persistent upregulation of CD74 could impair MHC class II antigen presentation, contributing to immune escape and promoting tumor metastasis." (PMID 37287976, 2023). "Persistent overexpression of CD74 on the cell surface could impair MHC class II antigen presentation by tumour cells, thereby contributing to immune escape and promoting tumour metastasis." (PMID 35208514, 2022). "Cancer cell-derived MIF or COPA potentially dictated the crosstalk with macrophages through CD74-related signaling pathways and, reciprocally, macrophage-secreted granulin (GRN) might send tumor-promoting signals to cancer cells via TNF receptors." (PMID 36198671, 2022). "CD74 was overexpressed in C4 /C9-CTLA4 CD4 T cell clusters, C5 and C6 /C4-GZMK CD8 T cell clusters, NSCLC tumor B cells, and suppressive tumor Tregs of CD4-C9-CTLA4 cells vs. other tumor-infiltrating Tregs of CD4-C8-FOXP3 cells." (PMID 35804895, 2022). "(F) Representative flow cytometry of tumor-propagating cells (TPCs) sorted after EHMT2 inhibitor (EHMT2i)- or vehicle control-treatment of primary tumorspheres and immuno-stained for AT2 markers SPC and CD74." (PMID 35983994, 2022). "Interestingly, in ACP tumor tissues, we found that CD74–APP and CD74–COPA interactions were also significantly strengthened between inflammatory activated microglia and neurons." (PMID 35525962, 2022). "Here, we assessed whether circulating tumor cells (CTCs) in peripheral blood can serve as a disease surrogate, focusing on CD44 and CD74 expression as prognostic markers for BM." (PMID 34209696, 2021). "In three cases (#15, #21 and #27), we found no CD74 immunoreactivity in tumor cells with UMAb231, but weak to moderate reactivity with LN-2 (panel a, black arrow)." (PMID 34944801, 2021). "Stainings were scored either in a categorical manner according to CD74 immunoreactivity levels in tumor cells only, as follows: 0 (absent), 1+ (weak), 2+ (moderate) or 3+ (strong) (respectively)." (PMID 34944801, 2021). "Given the involvement of many of these genes (such as C3, CD74, HLA-DR, STRA6, IGFBP4 and PIGR) in immune-mediated processes, it is tempting to speculate that their up-regulation indicates immune-mediated tumour control that is lost in malignant tumours." (PMID 32218455, 2020). "Milatuzumab binds to CD74, facilitating internalization of the antibody-CD74 complex, this is used to deliver conjugated antitumoral agents inside tumor cells with high CD74 expression, but not to normal cells with low CD74 levels." (PMID 29924850, 2018). "CD74 triggering by autocrine MIF may then enhance their ability to proliferate, as shown for tumor cells 39, and produce proinflammatory cytokines to mediate CNS pathology in MS." (PMID 30160778, 2018). "On evaluating gene array analysis of nonimmunogenic AgN2a cells compared to the parent immunogenic Neuro2a cell line, we identified down-regulation of several tumor immunosuppressive pathways, including PD-L1 (3.6-fold), CD47 (3.3-fold), CD74 (6-fold), and CD40 (2.3-fold)." (PMID 29377881, 2018). "In addition, it has been shown that in melanoma, IFN-gamma increases cell surface expression of CD74, and the interaction with its ligand MIF activates the PI3K/AKT pathway, promoting tumour survival." (PMID 29707160, 2018). "It has been shown that CD74 regulates the repertoire of antigens presented by MHCII and that this leads to primary engagement of CD4 and then CD8 components of the adaptive immune response, leading to tumor rejection." (PMID 27058619, 2017). "Therefore, it is reasonable that CD74 knockdown suppresses CSC via CD44, resulting in tumor growth inhibition in the xenograft model." (PMID 27626171, 2016).
tumor (continued). "Interestingly, MIF, which is secreted in response to hypoxia by different tumor cells, was reported to induce CD11b+GR1+ myeloid cell migration via CD74/CXCR4 and CD74/CXCR2 complexes, as well as through p38 and PI3K activation." (PMID 26347749, 2015). "Milatuzumab binds to CD74 and promotes internalization of the antibody-CD74 complex, thus delivering conjugated antitumoral agents inside tumor cells with high CD74 expression, but not to normal cells with low CD74 levels." (PMID 26441987, 2015). "A correlation was detected between tumor stromal CD74 expression and the tumor triple receptor-negative status (TRN), including the absence of ER itself." (PMID 24939415, 2014). "It was noted that in several instances (e.g., CD71 and CD74), the genes were not consistently detected within sequential tumor generations." (PMID 23405135, 2013). "Conversely, these cells may represent only a subpopulation of tumor stem cells found previously to display various combinations of CD24, CD74, and CD133." (PMID 20175927, 2010). "The altered relative ratio of the two transcript forms was however not accompanied by an overall increased Cd74 expression in tumor 01-762, compared to tumors with integrations elsewhere in the genome, as evaluated by Western blotting (data not shown)." (PMID 20416035, 2010). "Conversely, in certain contexts, particularly where CD74 co-expression with MHC-II supports antigen presentation, high CD74 expression may correlate with improved survival, likely reflecting increased immune visibility of tumor cells." (PMID 41597203, 2026). "However, in lobules with tumor invasion, NGFR+ stromal cells co-expressed the iCAF marker, PDGFRα, to a high extent (94%), while 22% of NGFR+ cells were positive for ASMA, and 34% for CD74." (PMID 41006303, 2025). "Studies have shown that MIF interacts with CD74 or CXCR2 and CXCR4 receptors, activating signaling pathways such as protein kinase B (AKT), extracellular signal-regulated kinases (ERK), and nuclear factor kappa-B (NF-κB), thereby promoting tumor proliferation, angiogenesis, and metastasis." (PMID 41562084, 2025). "The macrophage migration inhibitory factor (MIF), and its interacting partners CD74 and CD44 were highlighted, recognized for their roles in injury protection, healing promotion, and B cell survival, plays a pervasive role in mediating communications between tumor cells and macrophages." (PMID 40036264, 2025). "Furthermore, the interaction between the MIF pathway and its ligands, CD74/CXCR4, may play a important role in promoting tumor metastasis." (PMID 41127012, 2025). "CD74 is a type II transmembrane protein mainly expressed on antigen-presenting cells (APCs) such as macrophages, it can regulate the proliferation, survival, and secretion of inflammatory and fibrotic mediators in non-immune and non-tumor cells." (PMID 40755781, 2025). "The activation of the MIF - (CD74+CXCR4) axis indicates that IGF2BP1-overexpressing tumor cells may facilitate immune evasion through this pathway, consequently undermining anti-tumor immune responses and adversely impacting patient prognosis in immunotherapy contexts." (PMID 39512352, 2024). "The absence of CD74 significantly inhibited tumor development and growth." (PMID 39576827, 2024). "The inhibition of tumour growth by CD74 knockdown was observed solely in C57BL/6 mice, but not in immunodeficient mice, suggesting that CD74 may mediate its effects through interactions with T cells." (PMID 39113235, 2024). "Therefore, the enriched ligand-receptor pair of CD74-MIF mainly mediated the crosstalk among immune cells and tumor cells in the TME of HCC, possibly through activating macrophages and other immune cells, including B cells, CD8+ T cells and NKT cells, in the TME." (PMID 39118044, 2024).
tumor (continued). "Notably, CD44 was highly expressed on the tumor-enriched stressed CD56bright state, alongside CXCR4 and CD74, possibly sensitizing this population to TME-mediated immunosuppression from CAFs, fibroblasts, endothelial and tumor cells, as noted by high scores for TGF-β signaling, hypoxia and ROS." (PMID 38956379, 2024). "However, the lack of a discrete boundary between microglia and TAM cell clusters, and the distribution pattern of other myeloid markers (CD74, CD16, VISTA, and CD206), suggested the presence of multiple closely and distantly related myeloid subpopulations in the GBM tumor." (PMID 38758780, 2024). "Numerous studies have found that CD74 exerts an essential role in tumor immunity, but the expression profile of CD74 is still not systematically reported, and its value in human pan-cancer analysis is unknown." (PMID 38861249, 2024). "Despite the absence of PD-L1 protein expression data due to limited tumor tissue materials in this study, we inferred that the predictive value of CD74 protein expression might also be contributed by PD-L1 expression." (PMID 38280003, 2024). "The present study also brought evidence of NLRP7 involvement in the differentiation of tumor cells through the induction of embryonic markers such as NANOG, NOTCH1 and OCT3/4, and the activation of their survival through the induction of genes, such as CD74 and its co-receptor CXCR2." (PMID 36980199, 2023). "MIF also induces NF-κB activation through interactions with CD74 and enhances NF-κB target gene expression, including cellular inhibitors of apoptosis 2 (c-IAP2), Bcl-xl, MMP-2, uridylyl phosphate adenosine (uPA) and HIF-1α, facilitating the proliferation and migration of tumor cells." (PMID 35842634, 2022). "Moreover, we observed a reduced expression of HLA class II molecules (CD74, HLA-DRA, HLA-DRB1, HLA-DMA), which might affect the number and function of CD4+ T lymphocytes in the tumor microenvironment." (PMID 36153593, 2022). "In addition, CD74 expression was not significantly correlated with patient age, tumor size, ER, PR or HER2 status." (PMID 34944801, 2021). "We can conclude from the staining of whole slide sections of larger tumor specimens that CD74 appears to be heterogeneously expressed in different parts of a tumor, and the smaller biopsy cores from a TMA may not always represent the greater whole of a tumor." (PMID 34944801, 2021). "Thus, future studies are necessary to show whether this CD74 and CD44 induction on CTCs could be supportive of an active anti-tumor immune response in the blood flow." (PMID 34209696, 2021). "Moreover, high CD74 co-expression with immunosuppressive genes VEGFA and HIF1α and hematopoietic marker CD45 and tumor marker MultiKRT demonstrates that CD74 is expressed by both the tumor cells and the immune cells." (PMID 33228231, 2020). "CD74 is known primarily as the MHC class II invariant chain and functions in the molecular processing of MHC class II through the Golgi and a key factor in anti-tumor immunity as an important component in the functional presentation of MHC class II restricted antigens." (PMID 33327409, 2020). "We solely analyzed CD74 expression in tumor cells not in TAMs." (PMID 29490700, 2018). "As expected neither CD74 nor its co-receptor CD44 were detected in JL-1 tumor cells." (PMID 26883190, 2016). "In addition, CD74 regulates proliferation, survival, and secretion of inflammatory and fibrosis mediators in non-immune and non-tumor cells." (PMID 26441987, 2015). "The Cd74 expression levels, when evaluated on sections of a tumor and not at the single-cell level, could not in general be correlated with the status of proviral insertions within the locus." (PMID 20416035, 2010).